RNU7-120P (RNA, U7 small nuclear 120 pseudogene)
Gene: Small nuclear RNA gene on chromosome 12 (89,282,223 to 89,282,285, reverse strand). Ensembl gene ENSG00000238302.
Homologues: Orthologues: chimpanzee U7 (100% identical), macaque U7 (92% identical). Paralogues in human: RNU7-40P (83% identical), RNU7-123P (81% identical), RNU7-130P (81% identical), RNU7-136P (81% identical), RNU7-14P (81% identical), RNU7-24P (81% identical), RNU7-37P (81% identical), RNU7-48P (81% identical), RNU7-4P (81% identical), RNU7-62P (81% identical), RNU7-79P (81% identical), RNU7-7P (81% identical), and 142 more.